ZNF326 (zinc finger protein 326)
Description:
Core component of the DBIRD complex, a multiprotein complex that acts at the interface between core mRNP particles and RNA polymerase II (RNAPII) and integrates transcript elongation with the regulation of alternative splicing: the DBIRD complex affects local transcript elongation rates and alternative splicing of a large set of exons embedded in (A + T)-rich DNA regions. May play a role in neuronal differentiation and is able to bind DNA and activate expression in vitro.
Synonyms: ZIRD; Zfp326; ZAN75; FLJ20403; dJ871E2.1
Tractability: PROTAC: UniProt records ubiquitination sites on it; ubiquitination databases record sites on it; its protein half-life has been measured.
Gene: Protein-coding gene on chromosome 1 (89,995,110 to 90,035,533, forward strand). Ensembl gene ENSG00000162664.
Subcellular location: Nucleus matrix
Subcellular location (Human Protein Atlas): Nucleoplasm; Golgi apparatus; Vesicles
Gene Ontology:
Molecular function: protein binding; RNA binding; RNA polymerase II complex binding; DNA binding
Biological process: regulation of DNA-templated transcription; regulation of DNA-templated transcription elongation; regulation of RNA splicing
Cellular component: DBIRD complex; nucleus; nuclear matrix
Genetic constraint (gnomAD): Loss-of-function variants: 23 observed, 50.08 expected, observed/expected ratio (o/e) 0.46, 90% interval 0.33 to 0.65. The upper end of that interval is the gene's LOEUF score, 0.65, which puts it in group 2 of 6, group 1 being the genes least tolerant of losing a copy. Missense variants: 535 observed, 633.9 expected, observed/expected ratio (o/e) 0.84, 90% interval 0.79 to 0.91. Synonymous variants: 173 observed, 209.52 expected, observed/expected ratio (o/e) 0.83, 90% interval 0.73 to 0.94.
Homologues: Orthologues: chimpanzee ZNF326 (99% identical), macaque ZNF326 (98% identical), dog ZNF326 (92% identical), rabbit ZNF326 (92% identical), guinea pig ZNF326 (89% identical), mouse Zfp326 (86% identical), rat Zfp326 (86% identical), pig ZNF326 (84% identical), tropical clawed frog znf326 (53% identical), zebrafish znf326 (31% identical). Paralogues in human: AKAP8 (28% identical), AKAP8L (26% identical).
Diseases named in the same sentence as ZNF326 in open-access papers:
ZNF326 is named in the same sentence as 13 diseases in open-access papers, as found by Europe PMC text mining. Sharing a sentence is not in itself a finding about the gene and the disease. The quoted sentences say what the papers report.
glioma (6 papers, 2019 to 2022). A benign or malignant brain and spinal cord tumor that arises from glial cells (astrocytes, oligodendrocytes, ependymal cells). "This complex acts on mRNA particles and RNAII (polymerase), which regulates gene transcription and alternative splicing.These led us to explore the underlying role of ZNF326 in the development and progression of glioma." (PMID 30691485, 2019). "To conclude, ZNF326 expression is deregulated in human glioma, and its up-regulation is associated with tumour grade in patients with glioma." (PMID 30691485, 2019). "To verify whether ZNF326 has a causal role in regulating glioma cell phenotypes, we stably overexpressed ZNF326, using a lentivirus vector–based ZNF326 plasmid, in U87 and U251 cell lines." (PMID 30691485, 2019). "ZNF326 has been reported to bind to specific promoter regions through its transcriptional activation domain and zinc finger structure in glioma cells to activate HDAC7 transcription." (PMID 36227941, 2022). "Previous studies have showed that HDAC7 was involved in the malignant phenotype of glioma regulated by ZNF326." (PMID 32284070, 2020). "This study reveals the vital role and mechanism of ZNF326 in the malignant progression of glioma, and provides the reference for finding biomarkers and therapeutic targets for glioma." (PMID 30691485, 2019). "The effect of ZNF326 on glioma cells proliferation and invasion was conducted by functional experiments both in vivo and in vitro." (PMID 30691485, 2019). "In vitro and in vivo experiments verified that ZNF326 can promote glioma cell proliferation and invasiveness and tumour xenograft formation in nude mice." (PMID 30691485, 2019). "Our findings elucidated ZNF326 promotes the malignant phenotype of human glioma via ZNF326-HDAC7-β-catenin signalling." (PMID 30691485, 2019). "High nuclear expression of ZNF326 was observed in glioma cell lines and tissues, and closely related with advanced tumour grade in the patients." (PMID 30691485, 2019). "In this study, we report the clinical relevance of ZNF326 in glioma and its regulatory effect on the Wnt/β-catenin signalling pathway." (PMID 30691485, 2019). "Initially we measured the expression level of ZNF326 in human resected glioma specimens, and analysed the relationship between ZNF326 expression and clinicopathological factors of glioma." (PMID 30691485, 2019). "To explore a potential role of ZNF326 in glioma tumorigenesis, we performed IHC in a cohort of 133 human patients with glioma samples to examine the expression profiles of ZNF326." (PMID 30691485, 2019). "In this study, we uncovered that ZNF326 expression is upregulated in glioma specimens, which is also consistent with the result obtained from the TCGA database." (PMID 30691485, 2019). "B: Positive correlation between ZNF326 and the four common Wnt signalling pathway target genes in glioma, analysed at the GEPIA website." (PMID 30691485, 2019). "Consistently, compared with the ZNF326 IHC staining results, the expression of HDAC7 was positively correlated with the expression of ZNF326 in gliomas." (PMID 30691485, 2019). "Immunohistochemistry was applied to detect the expression of ZNF326 in glioma tissues, and statistical analysis was used to analyse the relationship between ZNF326 expression and clinicopathological factors." (PMID 30691485, 2019). "To verify this prediction, we first assessed the effect of ZNF326 on the activities of the Wnt pathway in glioma cell lines, using luciferase reporter assays." (PMID 30691485, 2019). "We found that nearly 60.9% (81/133) of patients with glioma had high level of nuclear ZNF326 (+, ++ and +++) in the glioma samples." (PMID 30691485, 2019). "To verify the impact of ZNF326 on the tumour growth of glioma cells in vivo, we evaluated the role of ZNF326 in tumour formation of U87 and U251 cells, using a xenograft model of nude mice." (PMID 30691485, 2019).
glioma (continued). "Until date, the expression of ZNF326 in human glioma, its effect on the malignant phenotype of glioma cells, and the possible signal transduction pathway involved have not been reported." (PMID 30691485, 2019). "We found ZNF326 transfection in glioma cells significantly increased the activity of the Wnt signalling pathway and its target gene expression, and there was an opposite effect upon ZNF326 knockdown." (PMID 30691485, 2019). "In summary, our findings demonstrated the expression level of ZNF326 in glioma tissue was positively correlated with its grades." (PMID 30691485, 2019). "In addition, ZNF326 is not only highly expressed in glioma, but also positively correlated with HDAC7 expression, thus confirming the role of HDAC7 oncogene." (PMID 36227941, 2022). "Furthermore, ZNF326 was not only highly expressed in glioma but was also positively correlated with the expression of HDAC7, which identified the oncogenic role of HDAC7." (PMID 35545840, 2022). "Some studies have reported that CELF1, DDX17 and ZNF326 are overexpressed in glioma." (PMID 34482818, 2021). "Therefore, ZNF326 promotes the malignant phenotype of human glioma via ZNF326-HDAC7-β-catenin signalling, which is one of its biological mechanisms." (PMID 30691485, 2019). "Altogether, these results suggest that ZNF326 could be used as a potential predictor of malignancy in gliomas." (PMID 30691485, 2019). "Zinc-finger protein-326 (ZNF326) was initially found in the NIH3T3 cell line to regulate cell growth, however, the expression and underlying role of ZNF326 in human tumours, especially in glioma, is not fully understood." (PMID 30691485, 2019). "Interestingly, we found that the expression of HDAC7 in NHA cell lines was also significantly lower than that in other glioma cell lines, similar to ZNF326 expression." (PMID 30691485, 2019). "We also investigated the effects of ZNF326 on the proliferation and invasiveness of glioma cells." (PMID 30691485, 2019). "Statistical analysis indicated high ZNF326 expression positively correlated with tumour grade, which hinted that ZNF326 might function as an oncogene in glioma." (PMID 30691485, 2019). "Moreover, ectopic ZNF326 expression promoted the proliferation and invasiveness of glioma cells." (PMID 30691485, 2019). "In addition, ZNF326 was negative in 5 cases of glioma tissues with grade-I and the ZNF326 staining was significantly associated with tumour grade (P = 0.000) and age (P = 0.012), but not with gender and tumour location." (PMID 30691485, 2019). "The close association that has been reported between Wnt/β-catenin signalling and glioma tumorigenesis, combined with our KEGG analysis, predicted that ZNF326 is closely related to the Wnt/β-catenin pathway." (PMID 30691485, 2019). "It was reported that ZNF326 could activate HDAC7 transcription by binding to a specific promoter region via its transcriptional activation domain and zinc-finger structures in glioma cells." (PMID 35545840, 2022). "IHC staining of ZNF326 and HDAC7 expressions in gliomas with different grades outlined below: (B, C): ZNF326 and HDAC7 were both negative expressed in pilocytic astrocytoma (grade I, Magnification 400×)." (PMID 30691485, 2019). "It is not clear why ZNF326 is overexpressed in gliomas, whether it is due to gene amplification, regulation of upstream genes or impaired metabolism, and whether the high expression of ZNF326 is tissue-specific, etc. need further study and confirmation." (PMID 30691485, 2019).
breast carcinoma (3 papers, 2020 to 2026). "ZNF326 is a nuclear transcription factor and acts as an oncoprotein in breast cancer, promoting the occurrence of EMT." (PMID 36081570, 2022). "PRMT5 and its substrate-binding partner WDR77 regulate alternative splicing through methylation of ZNF326 in breast cancer." (PMID 32392182, 2020).
depression (1 paper, 2012). "Genotype and allele distribution of ZNF326 polymorphisms in the controls, and in the patients with major depressive disorder and their responses to 8-weeks’ antidepressant treatment." (PMID 22666313, 2012). "Most importantly, polymorphisms of the human homologue of Zfp326, ZNF326, were found to be associated with therapeutic response to SSRI treatment in patients with major depressive disorder." (PMID 22666313, 2012). "By studying the function of Zfp326 or ZNF326, we may unravel the mechanism of antidepressant action and gain further insight into the pathology of major depressive disorder." (PMID 22666313, 2012).
tumor (4 papers, 2019 to 2022). "Two-step genetic screening in TNBC showed loss of ADNP, AP2B1, TOMM70A and ZNF326 in nude mice, of which further research on ZNF326, showed that it regulated tumor cell growth through effects on RNA splicing, epithelial-mesenchymal transition, and cancer stem-cell self-renewal." (PMID 30871273, 2019). "Further validation experiments revealed that ZNF326 is a tumor suppressor gene in TNBC and its knockdown resulted in an expression profile characteristic of an EMT in breast carcinoma cell lines." (PMID 36497409, 2022). "The analysis of the transposon integration sites identified several candidate genes, of which Man1a1, Pkp4, Rab10, Rasa1, Trps1, Vps26a, Xpnpep3 and Znf326 accelerated tumor growth, whereas the silencing of R3hcc1l reduced tumor growth." (PMID 36497409, 2022). "Both in vivo and in vitro experiments demonstrated that ZNF326 plays a role as a tumour-promoting factor through activation of the Wnt pathway." (PMID 30691485, 2019). "Stable expression of ZNF326 using lentivirus in U87 cells (selected with puromycin, 5 μg/mL) significantly promoted tumour growth in vivo when compared with that in the control group (CTL vs ZNF326, volume:0.168 ± 0.035 vs 0.400 ± 0.046, P < 0.01; weight:0.136 ± 0.024 vs 0.378 ± 0.056, P < 0.01)." (PMID 30691485, 2019). "To confirm the hypothesis above, we attempted to compare the effects of ZNF326 and ZNF326 + shRNA-HDAC7 on tumour growth." (PMID 30691485, 2019).
ZNF326 also shares sentences with these, for which no sentence is quoted: cancer (3 papers); anaplastic astrocytoma (1); colorectal cancer (1); glioblastoma (1); hepatocellular carcinoma (1); lymph node metastasis (1); pilocytic astrocytoma (1); psychosis (1); schizophrenia (1).